DYNC1H1 (dynein cytoplasmic 1 heavy chain 1)
Description:
Cytoplasmic dynein 1 acts as a motor for the intracellular retrograde motility of vesicles and organelles along microtubules. Dynein has ATPase activity; the force-producing power stroke is thought to occur on release of ADP. Plays a role in mitotic spindle assembly and metaphase plate congression.
Synonyms: DHC1; DNCH1; DNCL; DNECL; DYHC; Dnchc1; HL-3; p22; CMT2O; CDCBM13; DHC1a; SMALED1
Tractability: Small molecule: a structure with a bound ligand is known. Antibody: its Gene Ontology location is reachable by antibodies, with high confidence. PROTAC: ubiquitination databases record sites on it; its protein half-life has been measured.
Gene: Protein-coding gene on chromosome 14 (101,964,573 to 102,056,443, forward strand). Ensembl gene ENSG00000197102.
Subcellular location: Cytoplasm, cytoskeleton
Subcellular location (Human Protein Atlas): Cytosol; Annulus; Centrosome; Flagellar centriole; Mid piece
Pathways (Reactome):
Cell Cycle: AURKA Activation by TPX2; Amplification of signal from unattached kinetochores via a MAD2 inhibitory signal; EML4 and NUDC in mitotic spindle formation; Loss of Nlp from mitotic centrosomes; Loss of proteins required for interphase microtubule organization from the centrosome; Mitotic Prometaphase; Recruitment of NuMA to mitotic centrosomes; Recruitment of mitotic centrosome proteins and complexes; Regulation of PLK1 Activity at G2/M Transition; Resolution of Sister Chromatid Cohesion; Separation of Sister Chromatids
Immune System: MHC class II antigen presentation; Neutrophil degranulation
Vesicle-mediated transport: COPI-independent Golgi-to-ER retrograde traffic; COPI-mediated anterograde transport
Autophagy: Aggrephagy
Cellular responses to stimuli: HSP90 chaperone cycle for steroid hormone receptors (SHR) in the presence of ligand
Disease: HCMV Early Events
Organelle biogenesis and maintenance: Anchoring of the basal body to the plasma membrane
Signal Transduction: RHO GTPases Activate Formins
Gene Ontology:
Molecular function: dynein light intermediate chain binding; identical protein binding; minus-end-directed microtubule motor activity; protein binding; RNA binding; dynein intermediate chain binding; ATP binding
Biological process: establishment of spindle localization; positive regulation of intracellular transport; positive regulation of spindle assembly; regulation of metaphase plate congression; regulation of mitotic spindle organization; cytoplasmic microtubule organization; mitotic spindle organization; nuclear migration; P-body assembly; positive regulation of cold-induced thermogenesis; positive regulation of mitotic cell cycle spindle assembly checkpoint; retrograde axonal transport; stress granule assembly; microtubule-based movement
Cellular component: centrosome; cytoplasmic dynein complex; extracellular exosome; membrane; microtubule; azurophil granule lumen; cell cortex; cytoplasmic microtubule; cytosol; extracellular region; male germ cell nucleus; axon cytoplasm; cytoplasm; cytoskeleton; dynein complex; filopodium
Genetic constraint (gnomAD): Loss-of-function variants: 51 observed, 549.54 expected, observed/expected ratio (o/e) 0.0928, 90% interval 0.073 to 0.12. The upper end of that interval is the gene's LOEUF score, 0.12, which puts it in group 1 of 6, group 1 being the genes least tolerant of losing a copy. Missense variants: 2,769 observed, 6,249.4 expected, observed/expected ratio (o/e) 0.44, 90% interval 0.43 to 0.46. Synonymous variants: 2,189 observed, 2,386.5 expected, observed/expected ratio (o/e) 0.92, 90% interval 0.88 to 0.95.
Homologues: Orthologues: chimpanzee DYNC1H1 (99% identical), dog DYNC1H1 (99% identical), macaque DYNC1H1 (99% identical), mouse Dync1h1 (99% identical), rat Dync1h1 (99% identical), guinea pig DYNC1H1 (99% identical), pig DYNC1H1 (99% identical), tropical clawed frog DYNC1H1 (96% identical), Drosophila melanogaster Dhc64C (72% identical), Caenorhabditis elegans dhc-1 (55% identical), zebrafish dync1h1 (35% identical). Paralogues in human: DYNC2H1 (27% identical), DNAH9 (22% identical), DNAH10 (22% identical), DNAH11 (22% identical), DNAH17 (22% identical), DNAH2 (22% identical), DNAH5 (21% identical), DNAH1 (21% identical), DNAH6 (20% identical), DNAH8 (20% identical), DNAH7 (20% identical), DNAH3 (19% identical), and 3 more.
Diseases named in the same sentence as DYNC1H1 in open-access papers:
DYNC1H1 is named in the same sentence as 119 diseases in open-access papers, as found by Europe PMC text mining. Sharing a sentence is not in itself a finding about the gene and the disease. The quoted sentences say what the papers report.
Intellectual disability (20 papers, 2012 to 2025). "The observation of specific genotype–phenotype correlations, such as the increased association of intellectual disability with variants in DYNC1H1, ZC4H2, and TOR1A, is valuable for early prognosis and family counseling." (PMID 40443119, 2025). "Heterozygous DYNC1H1 variants are primarily associated with intellectual disability, cortical malformations, spinal muscular atrophy with lower-extremity predominance (SMA-LED), and the axonal neuropathy subtype CMT2O." (PMID 40869966, 2025). "Cognitive involvement, including individuals with intellectual disability and/or autism spectrum disorder, was observed in 27% of cases (27/100), mostly associated with pathogenic variants in DYNC1H1, TOR1A, and ZC4H2." (PMID 40443119, 2025). "DYNC1H1 variants are associated with a spectrum of neurodevelopmental disorders, such as spinal muscular atrophy, severe intellectual disability, and epileptic encephalopathies, with the majority of observed cases attributed to de novo variants." (PMID 40660528, 2025). "Mutations in the DYNC1H1 gene are responsible for intellectual disability and neuronal migration defects and play a role in neurodegenerative disorders." (PMID 40779003, 2025). "Apart from neuromuscular diseases such as SMALED1 and CMT2O, DYNC1H1 gene mutation is also related to intellectual disability characterized by early-onset seizures, mild dysmorphic features, and cortical malformations." (PMID 35899263, 2022). "Mutations in DYNC1H1 are associated with Charcot-Marie-Tooth disease, which is characterized by progressive weakness and atrophy, spinal muscular atrophy, and severe intellectual disability." (PMID 35177594, 2022). "Therefore, the mechanism of intellectual disability in patients with DYNC1H1 variants still needs further research." (PMID 34803881, 2021). "For example, DYNC1H1 (which encodes the heavy chain protein of the cytoplasmic dynein 1 motor protein complex) mutations cause a defect in neuronal migration causing brain development deficiencies that present as intellectual disability." (PMID 34552920, 2021). "Furthermore, we observed that the de novo mutations of DYNC1H1 were identified in several different neuropsychiatric disorders including EE, autism spectrum disorders and intellectual disabilities by previous studies, and these mutations primarily occurred in the functional domain of the protein." (PMID 28325891, 2017). "Intellectual disability was universally present in individuals with variants in ZC4H2 (5/5), DYNC1H1 (4/4), TOR1A (2/2), KAT6B (1/1), GLDN (1/1), and GPC3 (1/1), signifying a strong association between these genes and cognitive deficits." (PMID 40443119, 2025). "Mutations in the DYNC1H1 gene are also associated with autosomal dominant mental retardation-13 (MRD13), a form of intellectual disability linked to defects in neuronal migration, which result in malformations of the cerebral cortex." (PMID 40428333, 2025). "DYNC1H1-NDD variants mostly cluster in the motor regions and cause varying degrees of intellectual disability including learning and speech impairment." (PMID 36882741, 2023). "Notably, it has been observed in individuals exhibiting clinical features consistent with DYNC1H1-related intellectual disability (data unpublished by Invitae)." (PMID 38328757, 2023). "After consolidating intellectual disability gene lists from two databases and one recent review article, we identified eight LRRK2 interacting proteins that have previously been linked to intellectual disability: ACTB, ACTG1, ATRX, DYNC1H1, HERC2, PPP2R1A, TUBA1A, and YWHAE." (PMID 31963867, 2020). "A review of these cases showed that patients with DYNC1H1-related MCD had higher risks of epilepsy (odds ratio [OR] = 33.67, 95% confidence interval [CI] = 11.59, 97.84) and intellectual disability/developmental delay (OR = 52.64, 95% CI = 16.27, 170.38)." (PMID 37181555, 2023).
spinal muscular atrophy (14 papers, 2015 to 2025). A motor neuron disease that affect the muscles, and characterized by muscle weakness and atrophy resulting from progressive degeneration and irreversible loss of the anterior horn cells in the spinal cord (i.e., lower motor neurons) and the brain stem nuclei. "Dynein 1 impairment has been implicated in a spectrum of neurological diseases, with pathogenic variants in the DHC subunit DYNC1H1 linked to neuromuscular disorders including spinal muscular atrophy and peripheral neuropathy, as well as mental retardation." (PMID 33810506, 2021). "DYNC1H1 variants can be associated with peripheral nerve disease ranging from fetal akinesia to spinal muscular atrophy with lower extremity predominance." (PMID 32895508, 2020). "Another recent study reported a novel de novo mutation in DYNC1H1 presenting with the clinical phenotype of sporadic congenital Spinal Muscular Atrophy-Lower Extremity Dominant (SMA-LED) and EE30." (PMID 28325891, 2017). "Although the human pathogenic variant linked to peripheral neuropathy has not been characterized in the context of mitochondrial function or transport, fibroblasts from patients with DYNC1H1 variants causing spinal muscular atrophy exhibit fragmented morphology." (PMID 33810506, 2021). "Variants in the DYNC1H1 gene result in impairment of retrograde axonal transport leading to progressive motor neuron degeneration in mice and have been described in a range of neurogenetic diseases, including Charcot–Marie–Tooth type 2O, spinal muscular atrophy, and hereditary spastic paraplegia." (PMID 31475037, 2019). "Finally, the SPG11 p.Ser559Thr which was identified in a pyramidal sALS patient and the three DYNC1H1 variants, a gene previously associated with AD CMT2 and spinal muscular atrophy (SMA) phenotypes, were all classified as VUS." (PMID 32397312, 2020).
epilepsy (8 papers, 2017 to 2025). A brain disorder characterized by episodes of abnormally increased neuronal discharge resulting in transient episodes of sensory or motor neurological dysfunction, or psychic dysfunction. "Given that missense variants in the DYNC1H1 gene are strongly associated with epilepsy and benign variants in this gene are rare, the PP2 criterion was satisfied." (PMID 40660528, 2025). "Epilepsy is a common phenotype associated with DYNC1H1 gene variants, accounting for nearly 40% of cases in previous studies, with the majority exhibiting drug-resistant epilepsy." (PMID 40660528, 2025). "We further summarized the clinical, genetic, and neuroimaging characteristics of patients with DYNC1H1 variant-associated epilepsy from the relevant literature." (PMID 36636459, 2022). "Until now, few cases have described the epilepsy treatment of patients with DYNC1H1 variant in detail." (PMID 34803881, 2021). "Within this genetic interaction network, 12 high-confidence genes associated with epilepsy were detected in the network analysis of DYNC1H1, in addition to 9 genes for RTP1." (PMID 28325891, 2017). "The results revealed that DYNC1H1 was associated with 41 epilepsy-associated genes obtained from the EpilepsyGene database to different extents." (PMID 28325891, 2017). "In addition, most DYNC1H1 mutations in the motor domain are correlated with abnormal brain functions, such as epilepsy and global development delay." (PMID 35899263, 2022). "Patients with pachygyria carrying DYNC1H1 variants manifested epilepsy." (PMID 34803881, 2021). "A total of 18 articles found DYNC1H1 gene associated with epilepsy." (PMID 34803881, 2021). "We also reviewed previous literature about DYNC1H1 gene–associated epilepsy." (PMID 34803881, 2021). "However, few studies have focused on the association between DYNC1H1 variants and epilepsy." (PMID 36636459, 2022). "Thus, DYNC1H1 may cause epilepsy by affecting other epilepsy-related gene function, such as interaction with other mutations present in their genomes or environmental factor." (PMID 34803881, 2021). "In this study, we reported a de novo missense variant in the DYNC1H1 gene associated with DEE, characterized by early-onset, drug-resistant epilepsy and neurodevelopmental abnormalities." (PMID 40660528, 2025). "The most common phenotype reported in DYNC1H1-related epilepsy is represented by West syndrome, but also, one case with CSWS has been described." (PMID 38397281, 2024). "To date, therapeutic data on DYNC1H1-related epilepsy remain scarce." (PMID 40660528, 2025). "Our findings expand the genotypic spectrum of DYNC1H1-related epilepsy and suggested KD might be an optimized treatment for drug-resistant DEE, providing valuable clinical insights for the management of these patients." (PMID 40660528, 2025). "Interestingly, co-expression and genetic interaction network analyses suggested that DYNC1H1 and RTP1 are tightly associated with known epilepsy genes." (PMID 28325891, 2017). "Overall, the co-expression and genetic interactions network analyses indicated that DYNC1H1 and RTP1 may share a similar role with several candidate epilepsy genes." (PMID 28325891, 2017). "Epileptogenic mechanisms linked to pathogenic variants of DYNC1H1 gene were not clear; MCD may be the reason; however, patients from previous and our studies without MCD could also have epilepsy." (PMID 34803881, 2021).
Lissencephaly (7 papers, 2020 to 2026). A spectrum of malformations of cortical development caused by insufficient neuronal migration that subsumes the terms agyria, pachygyria and subcortical band heterotopia. "DYNC1H1 is known to bind both bicd cargo adaptor (BICD2), a microtubule motor adaptor associated with SMA lower extremity–predominant 2, and lissencephaly 1 (LIS1), a dynein regulator associated with MCD/lissencephaly, which might explain why the variant of DYNC1H1 could lead to pachygyria or MCD." (PMID 34803881, 2021). "Note that pathogenic variants in DYNC1H1 have been linked to a similar lissencephaly pattern but without hypomyelination." (PMID 32895508, 2020). "Although NDEL1 variants have never been reported to cause lissencephaly in humans, previous studies have strongly linked NDEL1 to other lissencephaly genes such as LIS1 and DYNC1H1, making NDEL1 a good candidate gene for lissencephaly." (PMID 38194050, 2024). "In a recent summary of targeted sequencing studies for 17 genes in 811 patients with lissencephaly, a diagnostic rate of 81% was observed, in which > 99% of pathogenic variants were in LIS1, DCX, TUBA1A, or DYNC1H1, none of which are inherited in an autosomal recessive fashion." (PMID 33290415, 2020).
autism (6 papers, 2021 to 2025). Persistent deficits in social interaction and communication and interaction as well as a markedly restricted repertoire of activity and interest as well as repetitive patterns of behavior. "DYNC1H1 is a risk gene for autism (SFARI Eagle score = 13.45) which participates in several steps in vesicular trafficking including dynein-dynactin cargo adaptor complex formation/activity, retrograde transport and cellular transport." (PMID 40779003, 2025). "Interestingly, we also identified differential mRNA expression of several autism-related genes (Dbh, Aqp4, Neo1, and Dync1h1), which might contribute to alterations in the mice autistic-like phenotypes." (PMID 34645786, 2021).
microcephaly (6 papers, 2016 to 2024). A congenital or acquired developmental disorder in which the circumference of the head is smaller than normal for the person's age and sex. "Heterozygous mutations in the DYNC1H1 gene located on chr14:101,964,572-102,056,442 (OMIM #614563) can lead to autosomal dominant mental retardation-13 with cerebral cortical malformations or microcephaly." (PMID 34573370, 2021). "Heterozygous mutations in the motor domain of DYNC1H1 have been associated with autosomal dominant mental retardation-13 (MRD13) with neuronal migration defects [OMIM: #614563], in which a subset of patients also present with microcephaly along with a small cerebellum and/or brainstem." (PMID 28783747, 2017).
dyneinopathies (5 papers, 2016 to 2023). "Mutations in DYNC1H1 can lead to various developmental and degenerative diseases of the nervous system, which are nominated as a disease spectrum of “dyneinopathy” characterized by locomotor and motor system deficits, sensory system defects, and (or) brain morphology and function abnormalities." (PMID 35899263, 2022). "The genotype–phenotype correlation may reflect the pathogenesis underlying the dyneinopathy caused by DYNC1H1 mutations." (PMID 35899263, 2022). "In this multi-center study, we report the clinical course of ten pediatric patients with DYNC1H1-associated phenotypes with nine novel pathogenic variants, highlighting the broad clinical heterogeneity of dyneinopathies and proposing a new clinical classification for DYNC1H1-related disorders." (PMID 32788638, 2020). "We report only the second case of congenital cataracts and the first of gut dysmotility in a patient with DYNC1H1, thus expanding the spectrum of disease seen in DYNC1H1 dyneinopathies." (PMID 27754416, 2016). "Weight and height are normal in DYNC1H1-related disorders or dyneinopathy, suggesting that DYNC1H1 is not essential for body growth." (PMID 37443841, 2023). "DYNC1H1-related disorders or dyneinopathy encompasses a spectrum of overlapping disorders, ranging from exclusive neuromuscular phenotype or DYNC1H1–NMD, or peripheral dyneinopathy, to combined neuromuscular and central nervous system dyneinopathy, on either side of the spectrum." (PMID 37443841, 2023).
Pachygyria (5 papers, 2020 to 2024). Pachygyria is a malformation of cortical development with abnormally wide gyri with sulci 1,5-3 cm apart and abnormally thick cortex measuring more than 5 mm (radiological definition). "Posterior pachygyria is the cortical malformation most associated with DYNC1H1 mutations, but patients can have additional abnormalities or both pachygyria and polymicrogyria." (PMID 38491427, 2024). "Specifically, variants in DYNC1H1 appear to be an important cause of MCD, a family of neuronal migration disorders that includes lissencephaly, pachygyria, polymicrogyria, and microcephaly." (PMID 38491427, 2024). "Pathogenic variants in DYNC1H1 and KIF2A, which encode microtubule-associated motor proteins, also lead to a spectrum of MCDs, ranging from pachygyria to dysgyria." (PMID 32895508, 2020).
Cognitive impairment (4 papers, 2022 to 2025). Abnormal cognition is characterized by deficits in thinking, reasoning, or remembering. "Interestingly, four of the six patients with DYNC1H1 disease-causing variants presented with neurodevelopmental disorders or cognitive impairments." (PMID 37337091, 2024). "A study reported that stroke was associated with cognitive impairment and dementia in older adults, and the six RNA-binding protein (RBP) genes (POLR2F, DYNC1H1, SMAD9, TRIM21, BRCA1, and ERI1) might participate in the process by mediating the hypoxic responses and angiogenesis." (PMID 37006557, 2023).